TNF (tumor necrosis factor)
Diseases named in the same sentence as TNF in open-access papers (continued):
Sharing a sentence is not in itself a finding about the gene and the disease.
diabetes (continued). "Using LASSO feature selection followed by multivariable logistic regression, a diagnostic nomogram was developed incorporating TLR2, IL-6, TNF-α, ESR, age, and diabetes duration." (PMID 41788768, 2026). "TNF‐α, a central mediator of vascular inflammation and endothelial dysfunction, is usually elevated in diabetes." (PMID 41567175, 2026). "Functional enrichment analyses revealed enrichment in critical pathways including FoxO, TNF-α and TGF-β signaling, also implicated in diabetes complications." (PMID 42111789, 2026). "Immunohistochemical analysis confirmed that diabetes and doxorubicin exposure increased TNF-α, caspase-3, 8-OHdG, and TGF-β1 expression, all of which were attenuated by treatment." (PMID 41301727, 2025). "Patients with type 2 diabetes mellitus have higher plasma concentrations of pro-inflammatory cytokines, including IL-1β, IL-6, IL-8, IL-17, IL-18, TNF-α, IFN-γ, and TGF-β, according to research (T2DM)." (PMID 40149566, 2025). "During the progression of diabetes, both intrinsic apoptosis, triggered by mitochondrial dysfunction, and extrinsic apoptosis, mediated by tumor necrosis factor-α (TNF-α), contribute to β-cell failure." (PMID 40394690, 2025). "Biomarker Development: Further research is needed to identify and validate inflammatory biomarkers (e.g., IL-1β, TNF-α) for predicting diabetes progression and treatment response." (PMID 40218134, 2025). "Of the four patients with diabetes mellitus, one was treated with anti-TNF-α, and three with anti-IL-23." (PMID 40699767, 2025). "Future studies will experimentally elucidate the precise regulatory effects of AR on the AGE-RAGE, TNF, and IL-17 signalling pathways in diabetes and its complications, thereby deepening our understanding of its efficacy and underlying mechanisms in T2DM." (PMID 41141342, 2025). "diabetes was significantly higher in patients with active tuberculosis (P=0.02), as was the prior use of at least two TNF-inhibitors (P=0.03)." (PMID 40557175, 2025). "Gene expression decreased in other treated groups, although the relative expression of TNF‐α in the crocin group was lower than in other groups versus the diabetes group." (PMID 39607899, 2025). "The pathophysiology of diabetes mellitus resembles a state of chronic inflammation, with elevated levels of inflammatory cytokines such as interleukin-6 (IL-6) and tumor necrosis factor-α (TNF-α) in patients with type 2 diabetes." (PMID 40002398, 2025). "A multiple logistic regression analysis revealed that diabetes, BMI, serum IL-6 level 3 days post-op, and serum TNF-α level 3 days post-op are optimal indicators for predicting LFCN injury in patients undergoing DAA total hip arthroplasty." (PMID 40236989, 2025). "In Type 1 diabetes mellitus (T1D) a significant increase in the expression of interleukin-10 (IL-10) and tumor necrosis factor-alpha (TNF-α) genes has been observed." (PMID 40299229, 2025). "For example, earlier studies suggesting a crucial role of TNFα have spurred several TNFα-blockade clinical studies in individuals with metabolic syndrome or diabetes." (PMID 40874857, 2025). "The results of this study demonstrated that liraglutide slowed the pathological damage and improved motor deficits and mood abnormalities of mice with diabetic PD by inhibiting TNF-α-mediated necroptosis and neuroinflammation." (PMID 40606832, 2025). "Inflammation, a key driver of thrombosis, diabetes mellitus, and diabetes mellitus complications, was demonstrated in our results by the elevated TNF-α, RANTES, and MCP-1 levels in the T, D, and DT groups." (PMID 40002353, 2025). "The TNF pathway exemplifies how chronic inflammation is a common factor in complex diseases like diabetes and BC, emphasizing the importance of addressing systemic inflammation in therapeutic strategies." (PMID 40547917, 2025).
diabetes (continued). "Future research should explore markers of systemic inflammation such as IL-6 or TNF-alpha to complement the analysis of perilesional tissue and evaluate the influence of specific comorbidities such as diabetes or renal failure." (PMID 39859129, 2025). "Diabetes increased IL-10, IL-17, IL-22, and TNF-α levels, and reduced IL-1β levels in the colon of diabetic mice compared to non-diabetic controls, without altering the content of IL-4, IL-6, and TGF- β1." (PMID 40496562, 2025). "In diabetes, people often exhibit elevated levels of T cell activators such as TNF-α and IFN-γ, along with low-grade chronic inflammation, both of which are known to induce T cell senescence." (PMID 40362271, 2025). "The positive association between diabetes and IL-10 was mediated 14.7% by TNFR1, 8.1% by IL-6, and 13.1% by TNF-α independently." (PMID 41280118, 2025). "The chronic low-grade inflammation in diabetes promotes the release of inflammatory mediators such as IL-6 and TNF-α, which not only worsen endothelial cell damage but also increase blood vessel permeability and impede angiogenesis." (PMID 40620799, 2025). "Current evidence indicates that saffron can significantly reduce TNF-α levels in patients with type 2 diabetes mellitus (T2DM), a mechanism potentially mediated by the inhibition of the NF-κB pathway." (PMID 40842498, 2025). "In a randomized controlled trial, daily supplementation with 250 g of frozen red raspberry for 4 weeks was associated with significantly lower levels of inflammation biomarkers, particularly IL-6 and TNF-α, in adults with established type 2 diabetes mellitus." (PMID 41156509, 2025). "For example, chronic physical illnesses (eg, diabetes) can activate proinflammatory cytokines (eg, interleukin-6, tumor necrosis factor alpha), affecting blood-brain barrier permeability and leading to neuroinflammation." (PMID 40611696, 2025). "Inflammatory cytokines, including TNF-α, are thought to play a role in the development of this form of diabetes, as they do in spontaneous autoimmune diabetes." (PMID 41282287, 2025). "Diabetes leads to severe synovial inflammation and elevated TNF-α levels in obese KOA patients, upregulating pro-inflammatory factors and MMP-13, and damaging joints." (PMID 41158135, 2025). "The feedback regulation of TNF-α by glucose in the diabetes model creates a vicious cycle: high glucose levels stimulate the secretion of TNF-α, forming a vicious cycle of hyperglycemia→increased TNF-α→more severe hyperglycemia." (PMID 41334449, 2025). "In rats with STZ-induced diabetes, blood levels of inflammatory markers, tumor necrosis factor-α (TNF-α), and nuclear factor kappa-light-chain-enhancer of activated B cells (NF-κB) were elevated compared to healthy animals, indicating inflammatory stress." (PMID 40806520, 2025). "Previous studies in diabetes-related complications have demonstrated that MCP-1 is secondary to TNF-α in type 2 diabetes and MCP-1 signalling attenuates TNF-α expression." (PMID 40708812, 2025). "Pro-inflammatory cytokines such as interleukin-1 beta (IL-1β) and tumor necrosis factor-alpha (TNF-α) play pivotal roles in the pathogenesis of diabetes by directly impairing pancreatic beta-cell function and promoting systemic metabolic dysregulation." (PMID 40218134, 2025). "NLRP3/IL-6/IL-1/TNF-α expression was reduced, and diabetes/hyperglycaemia-induced oxidative stress was suppressed, as evidenced by decreased 8-isoprostane and elevated superoxide dismutase-2 levels in vitro and in vivo." (PMID 41214779, 2025). "A study has shown that SB can reduce intestinal inflammation induced by diabetes mellitus, and the concentrations of IL-1β and TNF-α in mice that ingested SB decreased." (PMID 39997745, 2025). "Tumour necrosis factor-α (TNF-α) is a multifunctional cytokine that plays a key role in chronic inflammatory conditions, such as hypertension and diabetes." (PMID 40422564, 2025).
diabetes (continued). "Hyperglycemia in diabetes increases TNF-α release, primarily from monocytes, macrophages, and renal cells." (PMID 39941397, 2025). "By modulating inflammatory markers such as CRP, IL-6, and TNF-α, exercise can help alleviate both the physical and psychological burdens of diabetes." (PMID 40860530, 2025). "Our study results indicate that in diabetic rats, LYC reduces the expression of Cas-3, IFN-α, IL-6, and TNF-α, crucial cytokines in the pathogenesis of diabetes." (PMID 39968090, 2025). "Sustained activation of the TNF signaling pathway has been verified in the pathogenesis of a series of human diseases, including diabetes, inflammatory bowel diseases, and autoimmune diseases, providing a new field of agents for the treatment of ailments." (PMID 40616345, 2025). "Diabetes also activates cytokines, such as tumor necrosis factor (TNF-α), interleukin-1β, and interleukin-6, which promote inflammation." (PMID 40489503, 2025). "In diabetes, we showed that TNF-α signaling was increased in wound fibroblasts, which functions to increase Setdb2 expression and represses fibroblast to myofibroblast transition." (PMID 41277557, 2025). "Chronic inflammation and oxidative stress are pivotal in the interplay between periodontitis and diabetes, with inflammatory cytokines such as tumor necrosis factor-alpha (TNF-α) and interleukin-1 beta (IL-1β) playing central roles in this connection." (PMID 40283848, 2025). "Studies have shown that taurine reduces levels of TNF‐α and IL‐6, both of which play key roles in the pathology of diabetes and cellular senescence." (PMID 40458841, 2025). "In parallel, an anti-inflammatory effect of inulin administration on DPN in diverse stages of diabetes was unveiled in this study by reducing pro-inflammatory LPS, IL-6, TNF-α and IL-17A and elevating anti-inflammatory IL-10." (PMID 41264657, 2025). "Diabetes prolongs the inflammatory response to Porphyromonas gingivalis, a common periodontal pathogen, with increased TNF-α production." (PMID 39852378, 2025). "Considering the cytotoxic impact of alloxan-induced diabetes on various organs, such as the brain, pancreas, liver, and kidneys, we analyzed TNF-α and IL-6 levels in brain and liver tissues at the end of the experiment." (PMID 41020842, 2025). "Our analysis identifies the TNF pathway as a crucial mediator in the interplay between BC and diabetes." (PMID 40547917, 2025). "This study provides critical molecular insights into the shared mechanisms of BC and diabetes, identifying the TNF pathway as a key therapeutic target to improve outcomes for patients with these interconnected conditions." (PMID 40547917, 2025). "Studies in animal models have shown that BAT transplantation restores euglycemia, lowers levels of pro-inflammatory cytokines such as interleukin-6 (IL-6) and tumor necrosis factor-alpha (TNF-α), and reverses clinical symptoms of diabetes." (PMID 41511338, 2025). "The markers of inflammation involved in the bidirectional relationship between OSA and diabetes are tumor necrosis factor-α (TNF-α), interleukin-6 (IL-6), and C-reactive protein (CRP)." (PMID 41155523, 2025). "A chronic condition characterized by low-grade inflammation occurs in diabetes, marked by elevated levels of pro-inflammatory cytokines such as TNF-α, IL-1, and IL-6." (PMID 40149566, 2025). "Our findings further support this model, demonstrating that HgCl2 exposure, in conjunction with diabetes, significantly enhances TNF-α and IL-6 levels in both the hippocampus and PFC when compared to diabetic rats without HgCl2 treatment." (PMID 40726602, 2025). "In diabetes, the nuclear factor kappa B (NF-κB) signaling pathway is activated, and the expression level of tumor necrosis factor-α (TNF-α) is increased, both of which contribute to muscle inflammation and degradation." (PMID 39832033, 2025). "Conversely, TNF mRNA levels were higher in diabetes, with a significant difference between normoglycemic and diabetic mice treated with vehicle." (PMID 41369370, 2025).
diabetes (continued). "For instance, ROS can increase in number by the overexpression of tumor necrosis factor (TNF), but overloaded ROS can drive nuclear factor kappa-B (NF-κ B) downstream signal transduction, which is closely referred to many complications of diabetes." (PMID 41567637, 2025). "Patients with diabetes who have proliferative retinopathy show heightened levels of inflammatory mediators, such as tumor necrosis factor-alpha (TNF-α), interleukin-1 beta (IL-1β), soluble interleukin-2 receptor (sIL-2R), and interleukin-8 (IL-8)." (PMID 40332476, 2025). "Both ND and diabetes groups contained similar frequencies of TNF‐ and granzyme B‐producing CD8+ T cells, with IFNγ and IL‐2 production being significantly increased in T1D and T2D compared with ND, respectively." (PMID 41367201, 2025). "Type 2 diabetes mellitus is strongly associated with elevated levels of IL-6, leptin, CRP, and TNF-α." (PMID 41155523, 2025). "Long-term Hyperglycemia promotes the synthesis and secretion of TNF-α in diabetes, thus enhancing osteoclast activity and accelerating bone loss, which is an important pathogenesis of diabetic osteoporosis." (PMID 40529421, 2025). "Here, stimulated Raman scattering (SRS) microscopy is utilized to investigate glycogen metabolism in live ECs exposed to a diabetes-mimicking milieu-high glucose and tumor necrosis factor (TNF-α)." (PMID 41298232, 2025). "Our data indicate that diabetes leads to a predominantly Th17-type immune response profile in the colon, due to increased levels of IL-17, IL-22, and TNF-α." (PMID 40496562, 2025). "In diabetes, an elevated TNF-α level amplifies inflammatory responses, creating a sustained pro-inflammatory microenvironment that exacerbates chronic liver injury and accelerates fibrosis progression." (PMID 40362271, 2025). "IL6 and TNF-α plays an important role in the development of inflammation-mediated diabetes and neuropathy." (PMID 41264657, 2025). "It was previously indicated that the levels of proinflammatory cytokines, including TNF-α, IL-1β, and IL-6, are increased as diabetes progresses." (PMID 40589410, 2025). "The three primary components of the TNF signaling pathway are TNF-α, TNF-R1, and TNF-R2, and the activation of TNF signaling is implicated in the pathogenesis of a number of human diseases, such as diabetes mellitus, cancer, and multiple sclerosis." (PMID 41154714, 2025). "Quercetin has been described as reducing MDA and neural nitrite levels, preventing falls in neural SOD and GSH levels following diabetes, and lowering TNFα and IL-1β levels in the sciatic nerve." (PMID 38534744, 2024). "The levels of TNF–α were significantly higher in the subgroups of patients with diabetes when compared to the control group (for A1, p = 0.002; for B and C, p < 0.001)." (PMID 38542165, 2024). "RS treatment significantly decreases the levels of proinflammatory cytokines, HbA1c, IL-6, TNF-α, and IL-1β in diabetes in the elderly." (PMID 38903985, 2024). "During the onset of diabetes, the circulatory levels of several pro-inflammatory cytokines, including TNF-α, are elevated." (PMID 38474427, 2024). "The JAK-STAT pathway is a crucial cell signaling pathway involved in the regulation of various cytokines and growth factors, including TNF-α, which plays a central role in diabetes development and neuroinflammation, contributing to the development of MCI." (PMID 38963109, 2024). "Specifically, individuals with elevated TNF-α levels tended to show higher incidences of diabetes, suggesting a potential link between inflammatory cytokines and metabolic disorders in our study group." (PMID 39149648, 2024). "It will also decrease gene expressions (IL-6, TNF-α), and will prevent the formation of diabetes complications, by preventing insulin resistance." (PMID 39674630, 2024). "in Wistar rats with induced type 2 diabetes mellitus reported that TNF-α serum levels decreased after co-treatment with pioglitazone and aqueous leaf extract of Epilobium parviflorum Schreb." (PMID 38256751, 2024).
diabetes (continued). "Chronic inflammation can be created by increasing the production of TNF-α which is characteristic of diabetes." (PMID 38406163, 2024). "Individuals with diabetes exhibit elevated levels of IL-6, TNF-α, and nesfatin-1, indicating a link betweeninflammation, glucose dysregulation, and diabetes advancement." (PMID 39132231, 2024). "The plasma MDA and TNF- α level of treatment group were significantly reduced (p<0.05) compared to diabetes control group." (PMID 38266537, 2024). "Patients with diabetes can have elevated levels of tumour necrosis factor-α (TNF-α) in their serum, leading to decreased GFR and vasoconstriction." (PMID 39456664, 2024). "Diabetes significantly increased serum levels of TNF-α and IL-6 in diabetic control rats and vehicle-treated rats compared to normal controls." (PMID 39144694, 2024). "Nevertheless, during all studied time intervals, diabetes patients had lower TNF-α levels than healthy control subjects did." (PMID 38373910, 2024). "Inflammatory processes are initiated during diabetes, resulting in the formation of inflammatory molecules such as tumor necrosis factor α (TNF-α), interleukin 1β (IL-1β), interleukin 6 (IL-6), and interleukin 18 (IL-18)." (PMID 39684653, 2024). "Vascular calcification is related to diabetes mellitus (DM), in which several signaling pathways, such as TNF-α, and ILs, contribute to the development of vascular calcification." (PMID 38540696, 2024). "Diabetes mellitus is considered as inflammatory disease due to presence of cytokines such as interleukin (IL)-6 and TNF-α which rose in the blood of diabetic patients." (PMID 38528644, 2024). "The retina from humans with diabetes showed a significant increase in the expression of the pro-inflammatory TNF-α." (PMID 39728692, 2024). "As such, in our ApoE KO mouse model, we found an upregulation of TNFα and IL-6 in dyslipidemic mice exacerbated by diabetes." (PMID 38390337, 2024). "At the same time, chronic periodontitis with high TNF-α activity can increase systemic inflammation, further aggravating insulin resistance and making diabetes control more difficult." (PMID 39409052, 2024). "The clinical implication is based on the findings on the levels of TNF-α in oral carcinogenesis and its relationship with diabetes." (PMID 38406163, 2024). "Polyclonal anti-HMGB1 antibodies have also been implicated in neuropathic pain relief, reduction in neuronal degeneration, downregulation of pro-inflammatory TNF-α, and the restoration of glycemic control in diabetes." (PMID 39682695, 2024). "The second enrichment pathway was the AGE–RAGE signaling pathway in diabetes complications, which also correlated with TNF-α signaling and inflammation." (PMID 38399804, 2024). "TNF‐α cytokine levels decreased significantly in the diabetes +25 mg/kg bW stevia group compared to the diabetes group (**p < .01)." (PMID 39479688, 2024). "This category includes prognosis, diabetes mellitus, dental implants, complications of type 2 diabetes mellitus, complications of periodontal therapy, tumor necrosis factor-alpha, metabolism of blood glucose, and glycated hemoglobin." (PMID 38644951, 2024). "Immune markers linking chronic periodontitis and diabetes, such as glycation dynamics and TNF-α, have been identified as reliable indicators of inflammation in gingival crevicular fluid and serum." (PMID 39337647, 2024). "This meta-analysis aimed to examine the influence of chia consumption on three inflammatory markers: CRP, IL-6, and TNF-α in individuals with type 2 diabetes mellitus or overweight." (PMID 39703891, 2024). "When CD80 was co-expressed with TNF-α or IL-2, a large proportion of mice developed severe pancreatitis and diabetes mellitus." (PMID 39777226, 2024). "After the initiation of obesity, the adipocytes constantly produce free fatty acids; the continuous production of these affects the macrophages, causing these to produce TNF-α and inhibiting GLUT 4, finally conditioning the development of diabetes." (PMID 38498532, 2024).